HIGD1B (HIG1 hypoxia inducible domain family member 1B)
Synonyms: CLST11240; CLST11240-15
Tractability: Antibody: UniProt predicts a signal peptide or a membrane-spanning region.
Gene: Protein-coding gene on chromosome 17 (44,844,791 to 44,850,480, forward strand). Ensembl gene ENSG00000131097.
Subcellular location: Membrane
Subcellular location (Human Protein Atlas): Cytokinetic bridge; Microtubules; Mitotic spindle
Gene Ontology:
Biological process: mitochondrial respirasome assembly
Cellular component: mitochondrion; membrane
Genetic constraint (gnomAD): Loss-of-function variants: 5 observed, 6.53 expected, observed/expected ratio (o/e) 0.77, 90% interval 0.4 to 1.56. That is too few expected variants to judge how well the gene tolerates losing a copy. Missense variants: 86 observed, 81.88 expected, observed/expected ratio (o/e) 1.05, 90% interval 0.88 to 1.26. Synonymous variants: 29 observed, 30.07 expected, observed/expected ratio (o/e) 0.96, 90% interval 0.72 to 1.32.
Homologues: Orthologues: chimpanzee HIGD1B (100% identical), macaque HIGD1B (95% identical), pig HIGD1B (85% identical), rabbit HIGD1B (84% identical), dog HIGD1B (83% identical), rat Higd1b (78% identical), mouse Higd1b (77% identical), guinea pig HIGD1B (70% identical), tropical clawed frog higd1b (48% identical), zebrafish higd1a (44% identical), Drosophila melanogaster CG11825 (30% identical). Paralogues in human: HIGD1A (43% identical), HIGD1C (43% identical), HIGD2A (31% identical), HIGD2B (31% identical).
Diseases named in the same sentence as HIGD1B in open-access papers:
HIGD1B is named in the same sentence as 7 diseases in open-access papers, as found by Europe PMC text mining. Sharing a sentence is not in itself a finding about the gene and the disease. The quoted sentences say what the papers report.
pituitary adenomas (2 papers, 2021). "Moreover, an increased expression of HIGD1B has been observed in cervical cancer and plurihormonal pituitary adenomas." (PMID 34026765, 2021). "Higd1b is anticipated in the progression of pituitary adenomas and tumorigenesis." (PMID 34884814, 2021).
gastric cancer (1 paper, 2024). A primary or metastatic malignant neoplasm involving the stomach. "According to Cox regression analysis, HIGD1B represents a separate risk factor for the prognosis of gastric cancer (p<0.01)." (PMID 39108265, 2024). "Thus, there is cause for us to believe that HIGD1B may be a promising biomarker for predicting the outcome of gastric cancer and guiding clinical immunotherapy and personalized treatment." (PMID 39108265, 2024). "Second, although we have validated the differential expression of HIGD1B in gastric cancer cells and normal gastric epithelial cells through partial experiments (qRT-PCR and Western-Blot), further validation in human tissues is still needed." (PMID 39108265, 2024). "The findings confirmed that HIGD1B in gastric cancer tissue was considerably greater (p<0.01) than adjacent tissue in both cohorts." (PMID 39108265, 2024). "Cox regression analysis revealed that age, stage, and HIGD1B expression are independent elements for predicting the outcome of gastric cancer." (PMID 39108265, 2024). "In the TCGA-STAD cohort, HIGD1B was discovered to be considerably higher in gastric cancer tissue as compared to normal gastric tissue (p<0.001)." (PMID 39108265, 2024). "Likewise, it was noticed that gastric cancer tissue had a higher expression of HIGD1B in comparison to 27 paired adjacent tissues (p<0.05)." (PMID 39108265, 2024). "In addition, researchers have confirmed the differential expression of HIGD1B in gastric cancer cells and gastric epithelial cells through partial experiments." (PMID 39108265, 2024). "Additionally, more study is required to determine the exact mechanism by which HIGD1B encourages the onset and progression of gastric cancer, and additional experimental data is required to bolster our hypothesis." (PMID 39108265, 2024). "According to these findings, HIGD1B may regulate the infiltration and differentiation of TIICs to form highly inhibitory TME, thereby inhibiting immune response, promoting immune escape, and worsening the prognosis for patients with gastric cancer." (PMID 39108265, 2024). "However, the role and significance of HIGD1B in gastric cancer have not yet been explored." (PMID 39108265, 2024).
lung adenocarcinoma (1 paper, 2024). A carcinoma that arises from the lung and is characterized by the presence of malignant glandular epithelial cells. "Additionally, HIGD1B is highly expressed in human lung adenocarcinoma and is associated with a worse outcome." (PMID 39108265, 2024).
cancer (5 papers, 2020 to 2025). A tumor composed of atypical neoplastic, often pleomorphic cells that invade other tissues. "According to the analysis of pan-cancer data downloaded from the TCGA database, HIGD1B was observed to be significantly upregulated in the tumor tissues of COAD, ESCA, HNSC, KIRC, LIHC, STAD, and THCA, but lowered in BRCA, KICH, LUAD, LUSC, and UCEC." (PMID 39108265, 2024). "GSEA analysis demonstrated that the HIGD1B is closely related to cancer formation and advanced pathways." (PMID 39108265, 2024). "Thus, our study expanded the roles of HIGD1B in cancer biology which need further validations." (PMID 34026765, 2021). "In contrast with previous research, HIGD1B showed lower expression levels in LUAD compared with normal samples in TCGA datasets, which was also observed in our LUAD patients and cell lines, probably due to different cancer characteristics, implying its dual function in carcinogenesis." (PMID 34026765, 2021).
Tumor (1 paper, 2024). "The low HIGD1B group showed higher infiltration of T cells CD4 memory activated B with anti-tumor effects, while the high HIGD1B group had more macrophage M2 infiltration." (PMID 39108265, 2024). "Moreover, patients with high HIGD1B expression exhibited a higher level of Tumor-infiltration immune cells (TIICs) and were more likely to experience immune escape and drug resistance after chemotherapy and immunotherapy." (PMID 39108265, 2024). "This study clarified the relationship between HIGD1B, TME, and TIICs and discovered a positive correlation with immune scores and infiltration of tumor-promoting immune cells (such as Tregs, MDSC, and M2 macrophages)." (PMID 39108265, 2024).
HIGD1B also shares sentences with these, for which no sentence is quoted: cervical cancer (1 paper); lung carcinoma (1).